IGF1 (insulin like growth factor 1)
Diseases named in the same sentence as IGF1 in open-access papers (continued):
Sharing a sentence is not in itself a finding about the gene and the disease.
iron overload (8 papers, 2014 to 2024). "Additionally, IGF-1 has been reported to play a protective role against liver damage associated with iron overload in a cirrhotic rat model, where IGF-1 treatment prevented increases in MDA, iron stores, and ROS." (PMID 39594505, 2024). "Besides, in patients with thalassemia major, which is often characterized by low BMD values and iron overload, the circulating IGF-1 levels and its binding protein are lower than those in the healthy individuals." (PMID 32934756, 2020). "Hypogonadism and marrow expansion seem to play an important role, but iron overload, deferoxamine toxicity, a defective growth hormone-insulin-like growth factor-1 axis and multiple endocrinopathies may represent additional causes of bone damage." (PMID 29991466, 2019). "Potential causative factors of shorter final height in TM patients without AHH compared to patients with AHH include genetic factors, previous severe iron overload, desferrioxamine “toxicity”, delayed puberty and defects in the growth hormone-insulin- like growth factor-1 (GH-IGF-1) axis." (PMID 26740862, 2016).
liver failure (8 papers, 2015 to 2025). A liver disease characterized by the liver losing or has lost all of its function. "These cytokines and liver failure cause inhibition of the expression and signaling of GHR in liver, which leads to reduced production of IGF-1 in liver and decreased IGF-1 levels in blood." (PMID 31791247, 2019). "HGF, IGF1 and VEGFA play central roles in protecting against hepatic damage under hepatic I/R conditions and some of these growth factors are being tested in clinical trials, for instance on patients with liver failure." (PMID 34444713, 2021).
malaria (8 papers, 2012 to 2025). Malaria is a serious and sometimes fatal disease caused by a parasite that commonly infects a certain type of mosquito which feeds on humans. "We previously demonstrated that human IGF1 ingested in a blood meal can induce cell signaling in the mosquito midgut that reduces malaria parasite development and extends mosquito lifespan." (PMID 24968248, 2014). "In this study, we show that midgut signaling by human IGF1 increased the synthesis of reactive oxygen species in midgut mitochondria and enhanced nitric oxide synthase gene expression, responses that inhibit malaria parasite development in the mosquito." (PMID 24968248, 2014). "Positive malaria test was associated with lower serum IGF-1 (-4.7 μg/L, 95% CI: -7.8, -1.6), but not after inflammation adjustment (1.3 μg/L, 95% CI: -1.9, 4.6)." (PMID 41093111, 2025). "The cord blood IGF-1 also is found to be lower during maternal malaria." (PMID 39492784, 2024). "Previously, we showed that insulin-like growth factor 1 (IGF1) within a physiologically relevant range (0.013–0.13 μM) in human blood reduced development of the human parasite Plasmodium falciparum in the Indian malaria mosquito Anopheles stephensi." (PMID 24968248, 2014). "A. stephensi can also respond to ingested human IGF1, which unlike insulin, declines in serum during malaria." (PMID 24968248, 2014). "However, decrease in IGF1 levels might be exacerbated in women con-infected with HIV and malaria." (PMID 31042729, 2019). "Our results indicate that IGF1-induced RNOS, rather than enhanced NF-κB-dependent innate immune responses, kill malaria parasites in the midgut of A. stephensi." (PMID 24968248, 2014).
metabolic acidosis (8 papers, 2014 to 2024). "Metabolic acidosis seems to be related to increased IR and to the enhancement of insulin-like growth factor-1 (IGF1)." (PMID 33406683, 2021).
necrotizing enterocolitis (8 papers, 2020 to 2024). Necrotizing enterocolitis (NEC) is a devastating disease that affects mostly the intestine of premature infants. "Together, our results suggest that defective IGF-1-production by neonatal macrophages impairs neonatal intestinal microvascular development and predisposes the intestine to necrotizing enterocolitis." (PMID 35388142, 2022). "This study highlights the impact of macrophage-derived IGF-1 on the microvascular development in the neonatal intestine and a resulting protective effect against necrotizing enterocolitis." (PMID 35388142, 2022). "IGF-1 has thus been suggested to play a promising role in the treatment or prevention of necrotizing enterocolitis (NEC)." (PMID 34200323, 2021). "Poor general growth and low serum IGF-1 concentrations are associated with neonatal morbities such as ROP, intraventricular hemorrhage (IVH) and necrotizing enterocolitis (NEC)." (PMID 33489343, 2020).
overnutrition (8 papers, 2008 to 2026). An imbalanced nutritional status resulting from excessive intake of nutrients. "Overnutrition was associated with the lowest GH peak but the highest IGF-1 SDS; the opposite results were observed in undernutrition." (PMID 42123063, 2026). "Maternal IGF-1 signaling stimulates fetal growth through increased amino acid transport, inducing overnutrition and activating the fetal IGF-1 axis, whose components have been correlated with newborn birth weight." (PMID 40362828, 2025). "Obese subjects are known to have elevated circulating IGF-1 levels as a result of overnutrition, and it is therefore plausible that a high GL diet in people with a higher BMI has a more profound effect on IGF-1 levels." (PMID 18665189, 2008). "Nutrition is a key factor affecting IGF-1 synthesis and secretion, and IGF-1 levels are dysregulated in the condition of undernutrition or overnutrition, but the relationship between body mass index (BMI) and IGF-1 levels remains unclear." (PMID 37111069, 2023). "Although the efficiency of GH and IGF-1 as a treatment paradigm in the setting of maternal UN has been reasonably well explored in the rodent, less is known about the effect of such interventions in the setting of maternal overnutrition." (PMID 28786951, 2017).
panhypopituitarism (8 papers, 2011 to 2026). Insufficient production of all the anterior pituitary hormones. "Panhypopituitarism can be differentiated from isolated CCH by normal levels of ACTH, cortisol, IGF1/IGFBP3, LH, FSH, and prolactin." (PMID 22606512, 2011). "Panhypopituitarism was excluded by the findings of normal serum levels of ACTH, cortisol, IGF1, IGFBP3, LH, FSH, cortisol excretion in a 24-hour urine, and blood glucose profile." (PMID 22606512, 2011).
peripheral nerve injury (8 papers, 2018 to 2025). Injury to a peripheral nerve. "One of our current studies showed that IGF-1 signaling overactivation contributed to the development of neuropathic pain caused by peripheral nerve injury, implying that overdose rIGF-1 might even aggravate PDN." (PMID 35401920, 2022). "Previous studies reported that depletion of CD11c+ microglia or inhibition of IGF1/IGF1R signaling reinstated pain hypersensitivity in peripheral nerve injury models." (PMID 41276799, 2025). "Insulin-like growth factor-1 (IGF-1) is upregulated in the injured peripheral nerve bundle and controls nociceptive neuronal excitability associated with peripheral nerve injury." (PMID 31861182, 2019). "Major neurotrophic factors, such as IGF1, IGF2, NGF, BDNF, NT-3, and NT-4/5 can be produced by macrophages and are greatly upregulated in peripheral nerve injury, often concurrent with the influx of macrophages." (PMID 29907154, 2018).
renal carcinoma (8 papers, 2019 to 2024). A carcinoma arising from the epithelium of the renal parenchyma or the renal pelvis. "IGF-1 also induced survivin in renal cancer cells, and this effect was associated with proliferation." (PMID 30729097, 2019). "Increased levels of tumorigenic molecules, such as insulin-like growth factor 1 (IGF-1), are associated with several types of cancer, e.g., mammary, ovarian, prostate, gastrointestinal, liver, and renal cancer." (PMID 34444990, 2021). "Based on previous research and our study, we chose IGF1 as an AKT agonist and used it to stimulate AKT expression in renal carcinoma cells after nobiletin treatment." (PMID 31354472, 2019).
retinal degeneration (8 papers, 2013 to 2025). Degeneration of the retina. "In this concept, in Igf1 deficient mice, the malfunction of microglia during aging can lead to the establishment of a chronic low-grade inflammatory environment, favoring the onset and further progression of retinal degeneration." (PMID 30026694, 2018). "Also, it is well known that IGF-1 actions are slowed during aging and under this condition the deficiency of Igf1 in mice reflects an unbalanced anti-inflammatory vs. proinflammatory response in the retina that parallels the retinal degeneration." (PMID 30026694, 2018). "However, these intraocular IGF-1 overexpressers also exhibited retinal degeneration, gliosis, and decreases in rod and cone function similar to the global IGF-1 knockdowns, indicating that the role of IGF-1 in the retina is complex and levels are finely tuned." (PMID 35356301, 2022). "We hypothesize that PEDF and IGF-1 are likely at least partially responsible, although this prediction would require further experimentation in a more sophisticated model of retinal degeneration." (PMID 34768747, 2021). "Induction of chronic hypertension in an IGF-1-deficient mouse model exacerbated the development of cerebral microhemorrhage, with retinal vascular abnormalities and gliosis, but without signs of retinal hemorrhage and retinal degeneration." (PMID 37358957, 2023). "Similar to our findings from the circulating IGF-1 knockdown, global IGF-1 knockout animals exhibit signs of increased age-associated Müller cell gliosis in the retina but no overt retinal degeneration." (PMID 35356301, 2022). "The upregulation of PEDF and IGF-1 we identified in RPE-μTs has important therapeutic implications, as both molecules provide potent photoreceptor pro-survival signals and have been shown to rescue photoreceptors in retinal degeneration animal models." (PMID 34768747, 2021). "Thus, targeting neuroinflammation through the IGF-1/IGF-1R system and/or additional pharmacological strategies might conduct the regression of retinal degeneration and represents a challenging therapeutic strategy." (PMID 30026694, 2018).
stomach cancer (8 papers, 2005 to 2024). "This aligns with a previous study demonstrating the activation of the IGF1/IGF1R pathway in mesenchymal gastric tumors, which displayed sensitivity to Linsitinib (OSI-906), another selective IGF-1R inhibitor." (PMID 38962317, 2024). "INS, IGF1 and IGF2 CNV and relative overexpression were detected in 13% of gastric tumours." (PMID 34554347, 2022).
uremia (8 papers, 2011 to 2025). A clinical syndrome associated with the retention of renal waste products or uremic toxins in the blood. "Myostatin is a negative regulator of skeletal muscle mass, and an imbalance between IGF-1 and myostatin has been observed in experimental uremia models." (PMID 36632744, 2022). "Growth hormone (GH) resistance is common in uremia and together with resistance to insulin-like growth factor-1 (IGF-1) contributes to muscle wasting." (PMID 21655142, 2011). "Development of GH resistance in uremia stems from reduced IGF-1 synthesis, sensitivity or bioavailability, but also to impaired GH signal transduction." (PMID 21655142, 2011). "In addition, the hepatic resistance to GH-induced IGF-1 expression in uremia arises due to defects in STAT5b phosphorylation and its impaired binding to DNA, processes further aggravated by inflammation." (PMID 21655142, 2011). "A trend for a reduced level was observed for IGF-1 (p = 0.029) and ESR (p = 0.017), but no significant (p > 0.016) differences were found for HDL, TGs, conjugated and unconjugated bilirubin, uremia, serum creatinine, and HOMA %B." (PMID 39970875, 2025).
Acidosis (7 papers, 2016 to 2025). Abnormal acid accumulation or depletion of base. "In humans, chronic metabolic acidosis is associated with decreased serum IGF-1 concentration and is related to a resistance to the hepatocellular action of GH." (PMID 38556561, 2024). "Acidosis leads to loss of muscle mass through reducing protein synthesis and increasing proteolysis and amino acid oxidation, mediated via the ubiquitin proteasome system or via in IGF-1 signaling alterations." (PMID 31071141, 2019). "Acidosis directly disrupts the growth hormone (GH), insulin-like growth factor-1 (IGF-1) axis in the growing bone." (PMID 40978892, 2025). "Previous studies have found that in chronic metabolic acidosis, human serum IGF-1 concentrations are significantly reduced, and the response of IGF-1 to GH is diminished." (PMID 39917743, 2025). "The underlying mechanism is only partly understood but it is assumed to result from the combination of chronic hypoglycemia, lactic/keto-acidosis, and abnormal hormonal response, including growth hormone (GH)-insulin-like growth factor (IGF-1) axis alteration." (PMID 38556561, 2024).
acute myeloid leukemia (7 papers, 2010 to 2025). Acute myeloid leukemia (AML) is a group of neoplasms arising from precursor cells committed to the myeloid cell-line differentiation. "NR2F1-AS1 also exerts oncogenic effects by sponging miR-483-3p in acute myeloid leukemia (AML), enhancing IGF1 expression and fostering azacitidine resistance; in osteosarcoma, NR2F1-AS1 targets miR-483-3p to upregulate FOXA1, driving malignant progression." (PMID 41463366, 2025). "TEX produced by acute myelocytic leukemia (AML) cells induced widespread down-regulation of hematopoietic stem cell-supporting factors, such as CXCL12, KITL, IL-7, and IGF-1, in BMSCs and reduced their ability to support normal hematopoiesis." (PMID 37588208, 2024).
AIDS (7 papers, 2005 to 2025). A syndrome resulting from the acquired deficiency of cellular immunity caused by the human immunodeficiency virus (HIV). "The association of low plasma IGF1 (or IGF2) and high IGFBPs with HIV progression (AIDS, low CD4 T cell counts) have been well established." (PMID 25890304, 2015). "Older age (β coefficient = −1.31, P = 0.033), AIDS (β coefficient = −18.91, P = 0.081) and higher AST (β coefficient = −0.36, P = 0.026) were associated with lower plasma IGF1." (PMID 25890304, 2015). "IGF-1: IFG-1 may exert either pro- or anti-inflammatory effects in AIDs, depending on the target organs involved." (PMID 41383600, 2025). "However, these were largely performed in the pre-cART era and were focused on AIDS wasting, illustrating the opposite end of the spectrum of IGF-1 related pathologies." (PMID 28503671, 2017).
anxiety disorder (7 papers, 2017 to 2026). A category of psychiatric disorders which are characterized by anxious feelings or fear often accompanied by physical symptoms associated with anxiety. "Proinflammatory cytokines, including IL-6 and TNF-α, have been implicated in the etiologies of clinical anxiety disorders, which may affect the IGF-1 concentration." (PMID 37151979, 2023). "However, in other studies, individuals with depressive and/or anxiety disorders had higher IGF-1 concentrations than those without such disorders, which may indicate a response mechanism to counteract the impaired neurogenesis." (PMID 37151979, 2023).
benign breast disease (7 papers, 2007 to 2025). "Studies observed that both the variations of rs2132572 and rs3110697 were associated with increased IGF1 levels in the premenopausal women, and the variation in rs3110697 was associated with higher IGF1 levels in benign breast disease." (PMID 29100429, 2017). "Our findings showed that BV administration resulted in enhanced IGFBP-1 level and reduced IGF-1/IGFBP-1 ratio which both suggest that BV juice might potentially reduce IGF-dependent tumor progression toward malignancy from benign breast disease." (PMID 31752829, 2019). "The present study was designed to investigate the effects of Berberis vulgaris (BV) juice consumption on plasma levels of insulin-like growth factor (IGF-1), IGF-binding proteins (IGFBPs), and the expression of PPAR-γ, VEGF and HIF in women with benign breast disease." (PMID 31752829, 2019).
cholangiocarcinoma (7 papers, 2009 to 2026). A carcinoma that arises from the intrahepatic biliary tree (intrahepatic cholangiocarcinoma) or from the junction, or adjacent to the junction, of the right and left hepatic ducts (hilar cholangiocarcinoma). "Modulating PTPN9 expression influences IGF1-induced phosphorylation, affecting cholangiocarcinoma cell proliferation, migration, and invasion." (PMID 41275311, 2025). "In summary, our study delineates a previously underexplored CAF-derived IGF1/PTPN9-IGF1R signaling axis as a critical driver of cholangiocarcinoma progression and a key mediator of resistance to surufatinib." (PMID 41275311, 2025). "Recently was shown that CC express estrogens receptor (ER–α and –β) directly linked with insulin-like growth factor 1 (IGF1) and IGF1-R (receptor), which could represent a strategy for the management of cholangiocarcinoma." (PMID 27933122, 2009). "Studies have shown the role of IGF‐1 and IGF‐1R in regulating tumor cell growth in human cholangiocarcinoma and cholangiocarcinoma cell lines (Huh‐28, TFK‐1, MZ‐CHA‐1)." (PMID 40304434, 2025). "Furthermore, IGF1-driven IGF1R activation promotes tumor progression both in vitro and in vivo, while IGF1R inhibition via linsitinib effectively reduces these oncogenic effects, highlighting the significance of the PTPN9–IGF1R signaling axis in cholangiocarcinoma." (PMID 41275311, 2025).
chondrosarcoma (7 papers, 2002 to 2022). A malignant cartilaginous matrix-producing mesenchymal neoplasm arising from the bone and soft tissue. "The genetic polymorphisms in IGF-1 pathway members have also been correlated with elevated risk and poor prognosis of conventional chondrosarcoma patients in Chinese populations." (PMID 34069554, 2021). "Prior work demonstrated that MMP12 activation facilitates the migration and invasion of chondrosarcoma through IGF‐1 and VEGF signaling pathways." (PMID 35313071, 2022). "mRNA expression of the ligand IGF1 is restricted to four out of ten chondrosarcoma cell lines, with the highest expression in L835." (PMID 27418340, 2016). "Insulin-like growth factor 1 (IGF-1) can enhance the migration of chondrosarcoma cells by upregulating integrin expression." (PMID 24490159, 2013). "Indeed, IGF-1 modulated a5b1 integrin expression via the IGF-IR, PI3K, Akt, IKKa/b, and NF-kB-dependent pathway causing an increase in migration of human chondrosarcoma cells posing as an effective therapy tool." (PMID 34069554, 2021). "IGF-1 has also been correlated with a5b1 integrin-dependent human chondrosarcoma metastasis." (PMID 34069554, 2021). "This suggests that the IGF-1 signaling pathway may be another potential therapeutic target in chondrosarcoma." (PMID 24490159, 2013). "Even early reports have shown that IGF-1 and IGF-2 maintain, in an autocrine manner, the high PG synthesis in in vitro chondrosarcoma models." (PMID 34069554, 2021). "IGF-1 enhances both PG and p21 expression of SW1353 chondrosarcoma cells in a manner correlated with chondrosarcoma differentiation." (PMID 34069554, 2021). "Heterogeneous expression of IGF1R, IR, IGF2R, IGF1, IGF2, IRS1 and IGFBP3 was seen, both at the mRNA and protein levels, in chondrosarcoma cell lines." (PMID 27418340, 2016). "Treatment with three different IGF1R/IR inhibitors does not have an effect on chondrosarcoma cell viability, irrespective of apparent pathway activity and stimulation with IGF1." (PMID 27418340, 2016). "Furthermore, addition of IGF1 to the medium did not increase cell proliferation nor sensitivity to OSI-906 in three chondrosarcoma cell lines tested." (PMID 27418340, 2016). "One example of this is prevention of proliferation of an SRIF receptor-negative chondrosarcoma by the analogue SMS-201-995 via inhibition of growth hormone, insulin like growth factor-1 (IGF1) and insulin." (PMID 12085262, 2002).